BCL6 (BCL6 transcription repressor)
Diseases named in the same sentence as BCL6 in open-access papers (continued):
Sharing a sentence is not in itself a finding about the gene and the disease.
lung carcinoma (continued). "Our data demonstrated that mutational activation of KRAS robustly promoted BCL6 expression, and genetic depletion of BCL6 exhibited a profound inhibitory effect on KRAS-driven lung tumorigenesis, suggesting that BCL6 is a lynchpin for oncogenic KRAS dependence in lung cancer." (PMID 36377663, 2022). "Likewise, pharmacological inhibition of BCL6 significantly impeded the growth of KRAS-mutant lung cancer cells both in vitro and in vivo." (PMID 36377663, 2022). "Our study highlights the promise and merits of targeting BCL6 to treat KRAS-mutant lung cancer." (PMID 36377663, 2022). "To investigate the regulatory link between mutant KRAS and BCL6, we overexpressed different doxycycline-inducible G12 KRAS mutant variants (G12C, G12D, G12S, and G12V) in 293T cells, all of which commonly occur in human lung cancer." (PMID 36377663, 2022). "Importantly, the molecular regulation of BCL6 on preRC genes, such as MCM5 was functional and linked to clonogenic growth of KRAS-mutant lung cancer cells." (PMID 36377663, 2022). "Therefore, we determined BCL6 expression in an LSL-KrasG12D/+ mouse model of lung cancer." (PMID 36377663, 2022). "However, the role of BCL6 in lung cancer remains to be elucidated." (PMID 36377663, 2022). "However, the link between BCL6 and the initiation and progression of lung cancer remains unclear, particularly in the context of oncogenic drivers." (PMID 36377663, 2022). "BCL6 inhibition significantly triggered stalled replication forks and growth arrest, thereby blocking the malignant phenotype of KRAS-mutant lung cancer cells." (PMID 36377663, 2022). "In our study, we identified BCL6, a master regulator of germinal-center response, as a promoting factor for KRAS-mutant lung cancer." (PMID 36377663, 2022). "Our findings provide a direct link between BCL6 and KRAS oncogenic signaling and highlight that BCL6 is an important target for the treatment of KRAS-driven lung cancer." (PMID 36377663, 2022). "BCL6 maintained the global expression of prereplication complex components; therefore, BCL6 inhibition induced stalling of the replication fork, leading to DNA damage and growth arrest in KRAS-mutant lung cancer cells." (PMID 36377663, 2022). "This holds the promise of concurrent targeting of BCL6 and other KRAS pathway effectors, such as MEK, to treat KRAS-driven lung cancer." (PMID 36377663, 2022). "We recently revealed that BCL6 enables solid tumor cells to evade genotoxic stress, and pharmacological inhibition of BCL6 enhances the sensitivity of KRAS-mutant lung cancer cells to clinical BETi." (PMID 36377663, 2022). "Importantly, BCL6-specific knockout in lungs significantly reduced the tumor burden and mortality in the LSL-KrasG12D/+ lung cancer mouse model." (PMID 36377663, 2022). "Therefore, BCL6 inhibition dramatically impaired the initiation of DNA synthesis, leading to elevated replicative stress and DNA damage, specifically in KRAS-mutant lung cancer cells in vitro and in vivo." (PMID 36377663, 2022). "Given that the KRAS/MAPK/ELK1 axis directly regulates BCL6 expression, we next investigated whether activated BCL6 promoted KRAS-mutant lung cancer." (PMID 36377663, 2022). "Analysis of human lung cancer data sets derived from The Cancer Genome Atlas (TCGA) showed that KRAS, RAF1, MAP2K1, MAP2K2, MAPK3, and MAPK1 expression levels were positively correlated with the BCL6 expression level." (PMID 36377663, 2022). "Moreover, the combined inhibition of BCL6 and STAT3 synergistically defeats intratumoral heterogeneity in a subset of non–small cell lung cancers." (PMID 36377663, 2022). "Importantly, BCL6 was functionally required for KRAS-mutant lung tumorigenesis and tumor growth, as the genetic or pharmacological inhibition of BCL6 significantly impeded the growth of KRAS-mutant lung cancer in preclinical mouse models." (PMID 36377663, 2022).
lung carcinoma (continued). "Thus, there is a possibility that Pellino-1 might contribute to oncogenesis of lung cancer through BCL6 stabilization, which remains clarified by further study." (PMID 27248820, 2016).
melanoma (15 papers, 2011 to 2026). A malignant, usually aggressive tumor composed of atypical, neoplastic melanocytes. "The cellular composition of GCs in cutaneous melanoma metastases resembles that of control tonsillar tissue in that BCL6+CD20+ B cells and BCL6+CD4+ T cells are embedded within a network of CD21+CD23+ FDCs." (PMID 40940789, 2025). "Compared with human tonsil, germinal centers from human melanoma generally contained reduced numbers of both BCL6+CD20+ B cells and BCL6+CD4+ T cells." (PMID 34248957, 2021). "In a skin melanoma cohort from TCGA database, we observed increased proportion of lymph node metastasis in patients with higher Bcl6 expression in Treg cells, indicating that high level of Bcl6 in Treg cells may correlate with increased risk of metastasis of melanoma." (PMID 32477338, 2020). "In turn, the repression of Bcl-6 removes the brake from the overexpression of Blimp-1, which then leads to reduced numbers of PD-1 receptors on the surface of reactivated anti-melanoma effector cells." (PMID 30745900, 2019). "Mir-127 was previously shown to target BCL-6 in a bladder cancer model, so we first generated melanoma cell lines that ectopically express mir-127 in a stable manner." (PMID 22747855, 2012). "In addition, BCL6 maintains Foxp3 expression and promotes the suppressive ability of tumor-infiltrating Treg cells, and thus high BCL6 levels in Treg cells represent a poor prognosis marker in patients with colorectal cancer & melanoma." (PMID 34349770, 2021). "The rare observation of melanoma TLS with polarized germinal centers and Ki67+BCL6+ lymphatic cells gives a first hint that this ought to be possible." (PMID 34248957, 2021). "The expected continuous availability of tumor-associated antigens at melanoma sites together with our observation on the frequent lack of polarization of the mature FDC network rather argues more for a B cell receptor signaling-induced repression of BCL6 by comprehensive antigen presentation." (PMID 34248957, 2021). "Specifically, anti-melanoma CD8+ T cells overexpress PD-1 in the presence of large amounts of tumor-specific cytokines such as IL-6, a well-described regulator of Bcl-6 expression." (PMID 30745900, 2019). "Bcl6fl/fl CD4-cre mice, which lack BCL6 in both CD4 and CD8 T cells, starting at the double-positive stage of T-cell development, showed inhibited growth of MC38, LLC1 (Lewis lung carcinoma), and B16F10 (melanoma) tumors compared with Bcl6fl/fl control mice." (PMID 41145211, 2026). "Thus, depending on the tumor site, human melanoma metastases vary in terms of TLS density, particularly of extratumoral secondary follicular TLS with BCL6- germinal centers, and spatial distribution within intra- and extratumoral compartments." (PMID 34248957, 2021). "In contrast, melanoma germinal centers were smaller and had lower numbers of BCL6+, Ki67+ and BCL6+Ki67+ cells without polarized distribution (lower row)." (PMID 34248957, 2021). "As a result, Bcl-6 is overexpressed, while Blimp-1 is not expressed in the melanoma TME, which leads to the overexpression of PD-1 on the surface of anti-tumor CD8+ T cells." (PMID 30745900, 2019). "In our experimental system, mir-127 over-expression did not lead to a significant decrease in BCL-6 levels in melanoma cell lines, nor did it lead to a significant change in melanoma cell line proliferation or migration in vitro (results not shown)." (PMID 22747855, 2012). "Secondary follicular TLS in human melanoma metastases regularly contained key cellular and molecular components in a typical spatial arrangement, but only some larger secondary follicular TLS (21.7%) contained germinal centers that included BCL6+CD20+ B cells with interspersed BCL6+CD4+ T cells." (PMID 34248957, 2021). "Interestingly, secondary follicular TLS in melanoma often lacked BCL6+ lymphatic cells and canonical germinal center polarity with the formation of dark and light zone areas." (PMID 34248957, 2021).
melanoma (continued). "However, melanoma TLS with BCL6+ germinal centers often lacked germinal center polarization despite the expression of BCL6 in some germinal center B cells and T cells." (PMID 34248957, 2021). "To investigate the role of Bcl6 in Treg cells immune response during tumorigenesis, we first evaluated the expression pattern of Bcl6 in Treg cells in TME and tumor dLNs of wild-type (WT) mice intravenously implanted with B16-F10 melanoma cells (metastasis model)." (PMID 32477338, 2020). "Interestingly, BCL6- melanoma germinal centers showed no enrichment for Ki67+ cells." (PMID 34248957, 2021). "In the small number of melanoma brain metastases (n=3), secondary follicular TLS - and thus BCL6- germinal centers - were completely absent." (PMID 34248957, 2021).
B-cell CLL (14 papers, 2017 to 2024). "XPO1 E571K, a hotspot mutation in chronic lymphocytic leukemia (CLL) and PMBL, was also frequently identified in cases with MC signatures and was usually accompanied by the BCL6-trans signature." (PMID 32736575, 2020). "Furthermore, MYC translocations are a poor prognostic factor in DLBCL in association with BCL2 and/or BCL6 translocations, and MYC re-arrangements are also a driver of high-grade transformation in follicular lymphoma (FL) and chronic lymphocytic leukemia (CLL)." (PMID 36428647, 2022).
colorectal cancer (14 papers, 2015 to 2025). A primary or metastatic malignant neoplasm that affects the colon or rectum. "Integrating miR-155, VEGF, and immune-regulatory markers (e.g., SOCS1, BCL-6, IL-13RA1) into biomarker-based colorectal cancer detection models could enhance early detection and risk assessment." (PMID 41345725, 2025). "Importantly, the increased Bcl6 expression in Treg cells is associated with poor prognosis of human colorectal cancer and lymph node metastasis of skin melanoma." (PMID 32477338, 2020). "Here, we characterized a hypoxia-induced lncRNA LVBU (lncRNA regulation via BCL6/urea cycle) that is highly expressed in colorectal cancer (CRC) and correlates with poor cancer prognosis." (PMID 35906392, 2022). "We identify a deletion causing FOXC1 to gain an eQTL and enhancer in pancreatic cancer, and a duplication resulting in a gain of an eQTL for BCL6 in colorectal cancer." (PMID 34257393, 2021). "The occurrence of BCL6 in both cell compartments was also observed in microadenoma and colorectal cancer cells." (PMID 30832685, 2019). "Since we found Bcl-6 and its co-repressor BCoR (Bcl-6 interacting co-repressor) to be regulated in human microvascular endothelium by colorectal cancer cells, we investigated their function in sprouting angiogenesis which is central to tumor growth." (PMID 27880939, 2017). "Moreover, miR-144-3p inhibits cell proliferation of colorectal cancer cells by targeting BCL6, possibly through inhibition of Wnt/β-catenin signaling." (PMID 32206063, 2020). "Besides, Bcl6 expression in Treg cells reversely correlates with the prognosis of human colorectal cancer, while positively correlated with lymph node metastasis of skin melanoma." (PMID 32477338, 2020). "Moreover, the expression level of Bcl6 in Treg cells negatively correlates with the pathological grading of colorectal cancer, indicated by progressively increased proportion of Bcl6hi Treg cells from pathological stage I to stage IV (TNM stage) colorectal cancer patients." (PMID 32477338, 2020). "Interestingly, analysis of the independent human colorectal cancer cohort from TCGA (The Cancer Genome Atlas) database demonstrated that patients with higher level of Bcl6 (in Foxp3+CD4+ cells) showed significantly poorer overall survival compared to those with a lower level." (PMID 32477338, 2020). "Overall, the effect of the miR-144-3p/BCL6 axis on regulating CRC carcinogenesis was demonstrated, and miR-144-3p was identified as a potential prognostic and therapeutic target in colorectal cancer." (PMID 32206063, 2020). "The heatmap of individual samples, revealed a trend of high Bcl6, low Dlg2 and high MAPK9 in many colorectal carcinoma samples relative to the normal intestinal mucosa." (PMID 26187947, 2015). "In colorectal cancer, we observed various developmental stages of TLS within/around most primary tumors, from small LAs to mature TLSs which are characterized by the presence of a germinal center with BCL6+ and PD-1+ Tfh and CD11C+ DCs." (PMID 37768208, 2023).
MALT lymphoma (14 papers, 2012 to 2025). An indolent, extranodal type of non-Hodgkin lymphoma composed of small B-lymphocytes (centrocyte-like cells). "In immunohistochemistry, MALT lymphoma cells are CD20+, CD79a+, BCL2+, BCL6−, CD5−, CD10−, and CD23−." (PMID 35053607, 2022). "Typically, MALT lymphoma shows positivity for CD19, CD20, CD22, and CD79a, and negativity for CD3, CD5, CD10, CD23, BCL6, and cyclin D1." (PMID 33499258, 2021). "In our study, we found that the miRNA targeting BCL6 was miR-9-5p, which was downregulated in biopsy specimens of IgG4-ROD patients compared with orbital MALT lymphoma." (PMID 32764512, 2020). "Transformed MALT lymphomas are CD10− and BCL2−, but, in contrast to MALT lymphoma, they usually express BCL6." (PMID 25922601, 2015). "Tumours analyzed were CD20+, cyclin D1−, CD23−, CD5−, Bcl-6−, CD43−, and CD10−, supporting the diagnosis of MALT lymphoma." (PMID 23420489, 2013). "Immunophenotype can be determined either by immunohistochemistry or by flow cytometry, and MALT lymphomas are usually positive for CD19/20/22/79 and negative for CD5/10/23/BCL-6 and cyclin D1." (PMID 32908756, 2020). "MALT lymphomas are typically negative for CD5, CD10, BCL6 and cyclin D1." (PMID 34814897, 2021). "Similarly, the BCL6 and MUM1 positivity were not typical for a MALT lymphoma." (PMID 27213065, 2016).
hepatocellular carcinoma (13 papers, 2016 to 2026). A malignant tumor that arises from hepatocytes. "If we consider that the cells that express Bcl-6 are largely Tfh, our results are consistent with those indicating that impaired function of Tfh cells is associated with hepatocellular carcinoma progression." (PMID 27237631, 2016). "Herein, by analyzing the transcriptional factors which modulate differentially expressed genes between T cell infiltration high patient group and low group from TCGA data base, we found that BCL6 is a potential immune suppressor for hepatocellular carcinoma." (PMID 38956432, 2024). "Other potentially altered loops include a CTCF site near BCL6 in hepatocellular carcinoma and breast adenocarcinoma, and CLCN4 in colorectal adenocarcinomas." (PMID 32024999, 2020). "While BCL6 has been most widely studied in hematologic malignancies, some solid tumor data, such as hypermethylation of BCL6B correlating with metastasis in hepatocellular carcinoma, point to its involvement in metastatic behavior." (PMID 41597409, 2026). "However, the exact mechanism how Bcl6 affects hepatocellular carcinoma progression was not well elucidated." (PMID 38956432, 2024).
Infertility (13 papers, 2017 to 2026). "A combined immunostaining approach for CD56, CD138 and BCL-6 has shown diagnostic potential in unexplained infertility and guiding targeted therapies for reproductive failure." (PMID 40003650, 2025). "Immunohistochemical staining of BCL-6 in the endometrium has recently emerged as a new marker to be evaluated when the cause of infertility is in question." (PMID 37174948, 2023). "Abnormal B-cell CLL/lymphoma 6 (BCL6) expression in the endometrium of infertile women was found to be associated with endometrial P resistance." (PMID 31783865, 2019). "While surgical visualization and histological confirmation remain the diagnostic gold standard, integrating BCL6 testing into the clinical workflow for patients with unexplained infertility may help reduce diagnostic delays and improve patient outcomes." (PMID 41517625, 2026). "High BCL6 expression is also reported to be associated with poor reproductive outcomes in in vitro fertilization–embryo transfer cycles in women with unexplained infertility." (PMID 40358172, 2025). "Studies evaluating endometrial BCL6 expression on biopsy in infertile women were eligible if they reported reproductive outcomes or clinically relevant comparative data." (PMID 42279583, 2026). "We systematically reviewed the literature on endometrial BCL6 expression and reproductive outcomes in infertile women." (PMID 42279583, 2026). "Despite these limitations, emerging data support the potential value of a composite immune panel—including CD138+, CD56, and BCL-6—as the foundation for an “immune-mediated infertility” model." (PMID 41007809, 2025). "So far, a limited number of studies have investigated the possible involvement of BCL6 in infertility." (PMID 36294483, 2022). "The median of BCL6 intensity distribution in the endometrium of infertile women was found at 21.493 in the range of 4.451–54.822." (PMID 36294483, 2022). "We compared nine types of infertility in male humans and mice, including MArrest, oligospermia and teratospermia in humans and Ing2 Knockout (KO), Bcl6 KD, Etv5 KD, Pou3f1 KD, Ikbkap KO and Dazap1 mutant in mice." (PMID 29150651, 2017). "We previously reported over-expression of BCL6 in eutopic endometrium of infertile women with endometriosis." (PMID 28754906, 2017). "We previously demonstrated phosphorylation of STAT3 in eutopic endometrium of infertile women with this disorder leading to over-expression of the oncogene BCL6 and stabilization of hypoxia-induced factor 1 alpha (HIF-1α)." (PMID 28754906, 2017). "However, the prognostic and clinical significance of BCL6 across infertility settings remains incompletely defined." (PMID 42279583, 2026). "However, the clinical significance of the medical intervention for infertile women with high BCL6 expression remains controversial." (PMID 40358172, 2025). "Additionally, the endometrium in infertile women exposed to more exogenous progesterone had a significantly lower likelihood of high BCL6 expression." (PMID 40358172, 2025). "Stimulation of pro-inflammatory cytokines by BCL6 in the peritoneal fluid of these women could be responsible for infertility as well as recurrent miscarriages." (PMID 36294483, 2022). "As previously demonstrated by others, our data suggests a potential role for BCL6 in infertility." (PMID 36294483, 2022). "In all patients suffering from infertility, clear endometrial BCL6 expression was observed." (PMID 36294483, 2022). "After examining the cases with immunohistochemistry, the infertility center was advised to use CD56 positivity ≥6% and BCL-6 HSCORE ≥ 1.4 as references for the treatment options based on the previous literature." (PMID 37174948, 2023).